NOX4 (NADPH oxidase 4)
Description:
NADPH oxidase that catalyzes predominantly the reduction of oxygen to H2O2. Can also catalyze to a smaller extent, the reduction of oxygen to superoxide. May function as an oxygen sensor regulating the KCNK3/TASK-1 potassium channel and HIF1A activity. May regulate insulin signaling cascade. May play a role in apoptosis, bone resorption and lipolysaccharide-mediated activation of NFKB. May produce superoxide in the nucleus and play a role in regulating gene expression upon cell stimulation. Promotes ferroptosis, reactive oxygen species production and reduced glutathione (GSH) levels by activating NLRP3 inflammasome activation and cytokine release. [Isoform 4]: NADPH oxidase that catalyzes the generation of superoxide from molecular oxygen utilizing NADPH as an electron donor. Involved in redox signaling in vascular cells. Modulates the nuclear activation of ERK1/2 and the ELK1 transcription factor, and is capable of inducing nuclear DNA damage. [Isoform 3]: Lacks superoxide-generating NADPH oxidase activity.
Synonyms: KOX-1; RENOX; KOX
Tractability: Small molecule: a drug acting on it is in phase 2 or 3 trials; a high-quality ligand is known; it belongs to a druggable protein family. Antibody: UniProt places it where antibodies can reach, with high confidence; its Gene Ontology location is reachable by antibodies, with high confidence; UniProt predicts a signal peptide or a membrane-spanning region. PROTAC: a small molecule that binds it is known.
Target class: Enzyme; Oxidoreductase
Gene: Protein-coding gene on chromosome 11 (89,324,353 to 89,498,187, reverse strand). Ensembl gene ENSG00000086991.
Subcellular location: Cytoplasm; Endoplasmic reticulum membrane; Cell membrane; Cell junction, focal adhesion; Nucleus; Nucleus (Isoform 4); Nucleus, nucleolus; Cytoplasm, perinuclear region; Cytoplasm (Isoform 3); Cytoplasm (Isoform 5); Cytoplasm (Isoform 6)
Pathways (Reactome):
Disease: STAT5 activation downstream of FLT3 ITD mutants; Signaling by FLT3 fusion proteins
Cellular responses to stimuli: Detoxification of Reactive Oxygen Species
Gene Ontology:
Molecular function: heme binding; modified amino acid binding; NAD(P)H oxidase H2O2-forming activity; protein binding; superoxide-generating NAD(P)H oxidase activity; superoxide-generating NADPH oxidase activity; electron transfer activity; flavin adenine dinucleotide binding; nucleotide binding; oxygen sensor activity; protein tyrosine kinase binding; oxidoreductase activity
Biological process: gene expression; heart process; homocysteine metabolic process; superoxide metabolic process; cell morphogenesis; defense response; inflammatory response; intracellular signal transduction; negative regulation of cell population proliferation; reactive oxygen species biosynthetic process; superoxide anion generation; positive regulation of DNA biosynthetic process; positive regulation of ERK1 and ERK2 cascade; positive regulation of phosphatidylinositol 3-kinase/protein kinase B signal transduction; reactive oxygen species metabolic process
Cellular component: cytoplasm; endoplasmic reticulum; endoplasmic reticulum membrane; nucleus; perinuclear region of cytoplasm; plasma membrane; membrane; mitochondrion; NADPH oxidase complex; perinuclear endoplasmic reticulum; cell periphery; focal adhesion; nucleolus
Genetic constraint (gnomAD): Loss-of-function variants: 27 observed, 36.56 expected, observed/expected ratio (o/e) 0.74, 90% interval 0.54 to 1.02. The upper end of that interval is the gene's LOEUF score, 1.02, which puts it in group 4 of 6, group 1 being the genes least tolerant of losing a copy. Missense variants: 339 observed, 337.44 expected, observed/expected ratio (o/e) 1, 90% interval 0.92 to 1.1. Synonymous variants: 141 observed, 123.5 expected, observed/expected ratio (o/e) 1.14, 90% interval 1 to 1.31.
Homologues: Orthologues: chimpanzee NOX4 (99% identical), macaque NOX4 (98% identical), pig NOX4 (94% identical), dog NOX4 (94% identical), mouse Nox4 (91% identical), guinea pig NOX4 (89% identical), rabbit NOX4 (86% identical), rat Nox4 (85% identical), tropical clawed frog nox4 (66% identical), zebrafish NOX4 (25% identical). Paralogues in human: CYBB (38% identical), NOX3 (36% identical), NOX1 (35% identical), DUOX1 (28% identical), DUOX2 (28% identical), NOX5 (26% identical).
Diseases named in the same sentence as NOX4 in open-access papers:
NOX4 is named in the same sentence as 379 diseases in open-access papers, as found by Europe PMC text mining. Sharing a sentence is not in itself a finding about the gene and the disease. The quoted sentences say what the papers report.
diabetes (137 papers, 2008 to 2026). "Among other things, diabetes mellitus (DM) has been linked to impaired mitochondrial function or the stimulation of enzymes such as NADPH oxidase 4 (Nox4) that can contribute to excessive generation of ROS." (PMID 40806447, 2025). "Nox4 was initially named “Renox” due to its high constitutive activity in the kidney, its upregulation in diabetes, and its association with increased ROS production and renal injury." (PMID 38671903, 2024). "The significance of Nox4 expression and its associated ROS production in podocyte injury during diabetes was clearly established through using a podocyte-specific Nox4 knockout mouse model rendered diabetic via STZ injections." (PMID 38671903, 2024). "Diabetes mellitus promotes NOX4 expression in the podocytes and the production of ROS, leads to the loss of podocytes, and damages glomeruli, which indicates that NOX4 is an attractive therapeutic target for DN." (PMID 36874000, 2023). "These uncoupling NOS-derived events, in parallel with NOX4 activation described in the Section 4.2.1, contribute to endothelial cell dysfunction and renal damage related to diabetes-associated cardiovascular complications and nephropathy." (PMID 37298303, 2023). "Among the NOX isoforms, NOX4 is associated with diabetes where it dysregulates stress signaling, fibrosis, and insulin sensitivity in hepatocytes and Kupffer cells of liver and adipocytes." (PMID 33986669, 2021). "A significant finding in this study was that the administration of RLE for 24 weeks reduced the diabetes-associated up-regulation of both NOX4 and of the p47-phox and p22-phox subunits." (PMID 32466228, 2020). "Recent studies suggest that Nox5, either alone or together with Nox4, is predominantly responsible for the pathogenic renal ROS production in diabetes." (PMID 33396868, 2020). "Oxidative stress has been shown to cause diabetes-induced aortic endothelial dysfunction via NOX4 activation." (PMID 33273999, 2020). "At the end of the experiment, ZDF rats treated with RLE showed a reduction of the diabetes-associated up-regulation of both NOX4 and the p47-phox and p22-phox subunits, and restored the BAX/BCL-2 ratio respect to ZDF rats." (PMID 32466228, 2020). "Mitochondrial Nox4 is known as one of the important source of mitochondrial ROS in diabetes and aging associated cardiovascular disease." (PMID 31318905, 2019). "Nox4 deletion attenuated diabetes‐associated increases in albuminuria, glomerulosclerosis, and extracellular matrix accumulation." (PMID 25367693, 2014). "Furthermore, numerous studies have demonstrated that NOX2 and NOX4 activation underlies the perturbation in cellular homeostasis in diabetes." (PMID 33273999, 2020). "Recent studies have also linked increased activation of ADAM17 to Nox4 induction; thus, suggesting that this mechanism could be operational in diabetes-induced retinal microvascular injury." (PMID 32024241, 2020). "Prior studies have noted that the NADPH oxidase including NOX4 could cause renal tissue damage in diabetes." (PMID 32595756, 2020). "Moreover, NOX4 is also considered protective of diabetes-associated atherosclerosis in ApoE KO mice with STZ-induced diabetes." (PMID 31382355, 2019). "Nox4 has been implicated in renal injury in mouse models of diabetes, effects that are ameliorated with Nox1/4 inhibitors and in mice deficient in Nox4.54, 55 Nox5 may also be important in diabetes-associated vascular injury and nephropathy." (PMID 29459239, 2018). "However, during aging and in disease conditions, such as diabetes and cardiac hypertrophy, Nox4 is found in the mitochondria, which causes mitochondrial oxidative stress." (PMID 29710840, 2018). "Taken together, upregulation of Nox2 and/or Nox4 in the aorta may be linked to ROS overproduction and vascular dysfunction in our murine model of diabetes." (PMID 24485356, 2014).
diabetes (continued). "Indeed, in this study, we demonstrated that the diabetes‐induced increase in VEGF was attenuated in Nox4 KO mice associated with a normalization of nephrin expression and decreased expression of PKC‐α." (PMID 25367693, 2014). "PMA-stimulated CB-ECFC migration and tube-forming capacity observed in control cells was suppressed in experimental diabetes in parallel with reduced NOX4 expression and rescued by plasmid NOX4OE." (PMID 40457435, 2025). "It has been shown that, during the development of diabetes mellitus, the increase in the synthesis of renal angiotensin II contributes to the generation of superoxide anion radical in the kidney through NOX4 in mesangial cells and podocytes." (PMID 40076688, 2025). "Taken together, these data further support NOX4-dependent signalling as a key determinant of CB-ECFC angiogenic function in diabetes." (PMID 40457435, 2025). "Research has demonstrated that NADPH oxidase 1 (NOX1) acts as a pro-atherogenic and pro-oxidant factor, while NOX4 exhibits atheroprotective properties in STZ-induced diabetic Apoe+ mice, a widely used model for studying diabetes-associated atherosclerosis." (PMID 40076813, 2025). "A previous study demonstrated that NOX2 and NOX4 are involved in diabetes-induced muscle dysfunction." (PMID 40565097, 2025). "Regarding miR-146a, its expression in endothelial cells is reduced in patients with diabetes, leading to the increased expression of NADPH oxidase 4 (NOX4), thereby resulting in increased ROS production and endothelial damage." (PMID 40362167, 2025). "When HCtAECs were incubated with T2D RBC-EVs, we detected increased levels of NOX4, which is a key enzyme for superoxide production in diabetes." (PMID 40111409, 2025). "Studies have demonstrated that NOX4 is upregulated in response to various cardiovascular stressors, including heart failure, myocardial infarction, arrhythmias, and diabetes." (PMID 41009041, 2025). "In summary, the findings of this study clearly implicate NOX4 signalling as a critical regulator of CB-ECFC angiogenic (dys)function in diabetes." (PMID 40457435, 2025). "Previously, it has been shown in murine models of diabetes that the blockade of NOX4 leads to a reduction in albuminuria and that the overexpression of human NOX5 in podocytes and mesangial cells of diabetic mice exacerbates albuminuria." (PMID 38671844, 2024). "NADPH oxidase subunit NOX4 is a primary source of ROS and contributes to endothelial dysfunction in the setting of diabetes." (PMID 38580969, 2024). "On the other hand, NOX4 appears to have a vasculoprotective role, as the genetic deletion of Nox4 in mice led to accelerated atherosclerosis in diabetes." (PMID 38671844, 2024). "Nox4, the most abundant isoform of Nox present in the kidney, and another important Nox subunit p22phox have been reported to be involved in diabetes and hypertension." (PMID 38835661, 2024). "Given the pivotal role of NADPH oxidases, in particular Nox4, in ROS generation in retinal ECs, understanding how Nox4 upregulation and increased ROS mediate diabetes-induced vascular damage would have high translational significance." (PMID 38748682, 2024). "NOX4 has been proposed to contribute to vascular dysfunction in aging, diabetes and atherosclerosis, and it has shown to be upregulated in aortic tissue from rats with diet-induced obesity." (PMID 39334798, 2024). "Liraglutide was found to reduce diabetes-induced albuminuria and mesangial expansion, as well as attenuate glomerular Nox4 expression and oxidative stress." (PMID 38671903, 2024). "In rats with streptozotocin-induced diabetes, glycine has been shown to reduce renal oxidative stress by inhibiting Nox4 expression, thereby mitigating diabetic renal damage." (PMID 38807172, 2024). "As it can be seen diabetes induction significantly (male: p < 0.0001, female: p < 0.001) increased the NOX4 gene expression in both DC groups in compared to both NDC groups." (PMID 36755074, 2023).
diabetes (continued). "Recent reports have shown that SH3YL1 is a regulator of NOX4 and is a biomarker in animal models and patients with diabetes." (PMID 37109492, 2023). "Among the different NADPH oxidase isoforms, NOX4 was found to be the main enzyme contributing to increased oxidative stress in podocytes, as genetic ablation or the pharmacological inhibition of NOX4 activity attenuated DN in a rodent model of diabetes." (PMID 37103361, 2023). "The main function of NADPH oxidase is to catalyze the formation of reactive oxygen species, and renal NOX4 expression has been shown to be increased in podocytes and mesangial cells in the course of diabetes, contributing to CKD." (PMID 37047807, 2023). "Reduction of NOX4-mediated ROS production was protective in various diseases, including cardiac ischemia/reperfusion injuries, diabetes, and Streptococcus pneumonia infection as well as fibrotic progression." (PMID 37044213, 2023). "Gene profiling of ROS-related enzymes showed that diabetes elevated p47phox, Nox2, and Nox4 mRNA levels in WT mice." (PMID 35133981, 2022). "In sum, these data suggest that Sirt1-stimulated miR-182 can advance corneal neuronal regeneration and nerve density by way of targeting NOX4 in diabetes." (PMID 36670932, 2022). "In contrast, global NOX4 deletion can both protect against and aggravate diabetes‐induced atherosclerosis, depending on the time frame." (PMID 35386842, 2022). "Recently, the microbiota has been reported as a link between diabetes and cancer via an IL-1β and NADPH oxidase 4 dependent signaling cascade." (PMID 36499348, 2022). "NOX2 mRNA levels were upregulated in both muscles from the diabetes group, whereas NOX4 only was higher in EDL muscle compared to control rats, while in soleus muscle remained unchanged compared to all groups." (PMID 35629342, 2022). "As expected, treatment with apocynin reduced the level of expression of NOX2 in both muscles, and a lower-level expression of NOX4 was detected in EDL muscle compared to the diabetes group." (PMID 35629342, 2022). "NOX4 is the major NAD(P)H oxidase isoform in cardiomyocytes, which is associated with cardiomyopathy in the diabetes model." (PMID 35111238, 2022). "Evidence has shown that NOX4 deletion promoted diabetes‐induced plaque formation in the early stage, but in the progressive stage, NOX4 deletion helped to repress inflammation." (PMID 35386842, 2022). "NOX4 overexpression promotes podocyte injury and exacerbates albuminuria in animal models of diabetes." (PMID 36297636, 2022). "Excess ROS derived from Nox1 and Nox4 have been shown to contribute to diabetic retinopathy, an end-stage disease of diabetes mellitus, which threatens vision as a result of increased vascular permeability and neovascularisation." (PMID 34571964, 2021). "NOX2 and NOX4 have been detected in the aorta of ApoE−/− atherosclerotic mice models exposed to the streptozotocin diabetes inducer." (PMID 34205998, 2021). "Our past data indicated that Nox4 expression in the kidney is highest under quiescent conditions in healthy animals, whereas inflammation and diseases such as diabetes decreased Nox4." (PMID 34356336, 2021). "Diabetes increased the mRNA expression of p47phox, Nox2, and Nox4 in the renal cortex by 6.2 ± 4.6-fold, 3.6 ± 2.7-fold, and 1.3 ± 0.1-fold, respectively." (PMID 34977254, 2021). "Nox4 activity has also been shown to be increased in the serum of patients with type 2 diabetes mellitus." (PMID 34571964, 2021). "NOX4 is the major source of oxidative stress in neurodegeneration on ischemic stroke, diabetes, cardiovascular diseases, pulmonary fibrosis and hypertension." (PMID 32707664, 2020). "Nox4, as a major source of ROS production in beta cells, has been shown to be involved in the pathogenesis of diabetes." (PMID 32397640, 2020). "Previous studies have reported that angiotensin II is increased in diabetes and that angiotensin II inhibits PGC1α and activates NOX4 in the kidney as in other tissue." (PMID 33255934, 2020).